LHX3 (LIM homeobox 3)
Description:
Transcription factor. Recognizes and binds to the consensus sequence motif 5'-AATTAATTA-3' in the regulatory elements of target genes, such as glycoprotein hormones alpha chain CGA and visual system homeobox CHX10, positively modulating transcription; transcription can be co-activated by LDB2. Synergistically enhances transcription from the prolactin promoter in cooperation with POU1F1/Pit-1 (By similarity). Required for the establishment of the specialized cells of the pituitary gland and the nervous system. Involved in the development of interneurons and motor neurons in cooperation with LDB1 and ISL1 (By similarity).
Synonyms: CPHD3; LIM3; M2-LHX3
Tractability: No criterion of Open Targets' tractability assessment is met for any kind of drug.
Gene: Protein-coding gene on chromosome 9 (136,196,250 to 136,205,128, reverse strand). Ensembl gene ENSG00000107187.
Subcellular location: Nucleus
Pathways (Reactome):
Developmental Biology: Regulation of expression of SLITs and ROBOs
Gene Ontology:
Molecular function: DNA-binding transcription activator activity, RNA polymerase II-specific; RNA polymerase II-specific DNA-binding transcription factor binding; sequence-specific DNA binding; DNA-binding transcription factor activity, RNA polymerase II-specific; RNA polymerase II transcription regulatory region sequence-specific DNA binding; DNA binding; promoter-specific chromatin binding; transcription cis-regulatory region binding; transcription coactivator binding; transcription coregulator binding; zinc ion binding
Biological process: inner ear development; positive regulation of transcription by RNA polymerase II; animal organ morphogenesis; neuron differentiation; positive regulation of DNA-templated transcription; regulation of transcription by RNA polymerase II; regulation of DNA-templated transcription
Cellular component: chromatin; nucleus; transcription regulator complex
Genetic constraint (gnomAD): Loss-of-function variants: 22 observed, 30.67 expected, observed/expected ratio (o/e) 0.72, 90% interval 0.51 to 1.02. The upper end of that interval is the gene's LOEUF score, 1.02, which puts it in group 4 of 6, group 1 being the genes least tolerant of losing a copy. Missense variants: 626 observed, 519.18 expected, observed/expected ratio (o/e) 1.21, 90% interval 1.13 to 1.29. Synonymous variants: 258 observed, 223.88 expected, observed/expected ratio (o/e) 1.15, 90% interval 1.04 to 1.28.
Homologues: Orthologues: chimpanzee LHX3 (94% identical), macaque LHX3 (93% identical), mouse Lhx3 (90% identical), pig LHX3 (90% identical), guinea pig LHX3 (89% identical), rat Lhx3 (89% identical), dog LHX3 (89% identical), zebrafish LHX3 (62% identical). Paralogues in human: LHX4 (63% identical), LHX5 (38% identical), LHX1 (36% identical), LMX1A (31% identical), LMX1B (29% identical), ZFHX3 (28% identical), ZFHX4 (27% identical), LHX2 (24% identical), LHX9 (24% identical), LHX6 (23% identical), LHX8 (22% identical), ZFHX2 (21% identical), and 8 more.
Diseases named in the same sentence as LHX3 in open-access papers:
LHX3 is named in the same sentence as 41 diseases in open-access papers, as found by Europe PMC text mining. Sharing a sentence is not in itself a finding about the gene and the disease. The quoted sentences say what the papers report.
hypopituitarism (13 papers, 2012 to 2022). A condition of diminution or cessation of secretion of one or more hormones from the anterior pituitary gland. "TES showed monoallelic LHX3 mutation (c.935G.A) associated with combined pituitary hormone deficiency (CPHD)." (PMID 35806993, 2022). "The authors suggested an association between the LHX3 mutation in dogs with combined pituitary hormone deficiency and atlanto-axial malformations." (PMID 34370756, 2021). "Biallelic mutations in the LHX3 have been associated with combined pituitary hormone deficiency (MIM: #221750), characterized by impaired production of GH and other anterior pituitary hormones." (PMID 34589056, 2021). "Currently, three types of LHX3 autosomal recessive inheritance have been identified in humans, and all patients have multiple pituitary hormone deficiencies." (PMID 32733554, 2020). "In the pituitary, mutations in Lhx3 and Lhx4 are also the causes for combined pituitary hormone deficiency (CPHD), indicating that Ldb1/Lhx3/Lhx4 complex is indispensable for pituitary development." (PMID 30127719, 2018). "In the case of heterozygous LHX3 mutation, mild combined pituitary hormone deficiencies may occur." (PMID 34948037, 2021). "The pituitary transcription factors HESX1, LHX3, and SOX2 are vital for early patterning of the forebrain and pituitary, and mutations in these developmental genes result in syndromic hypopituitarism with gonadotropin deficiency in humans." (PMID 31220230, 2019). "Increased apoptosis later in development does contribute to the hypopituitarism observed in Lhx3 null embryos." (PMID 23284914, 2012). "HESX1, GLI2, and SOX3 mutations have been linked to hypopituitarism, and mutations in SOX2, LHX3, LHX4, and PROP1 may cause gonadotropin deficiency." (PMID 34948037, 2021). "The pituitary transcription factors LIM Homeobox 3(LHX3), SRY-Box 2 (SOX2) and HESX homeobox 1 (HESX1) are vital for early patterning of the forebrain and pituitary, and mutations in these developmental genes result in syndromic hypopituitarism with gonadotropin deficiency in humans." (PMID 29730183, 2018).
deafness (3 papers, 2013 to 2019). An inherited or acquired condition characterized by the complete loss of the ability to hear from one or both ears. "Moreover, the expression levels of the other nine deafness-related genes (Myo15, Gfi1, Lhx3, Barhl1, Pjvk, Tomt, Pou4f3, Tmc1, and Grxcr2) were downregulated more than 2-fold in DT-treated Prestin-hDTR mice." (PMID 30918314, 2019). "Intriguingly, an LHX3 mutation that causes specific deletion of the C-terminus (W224ter) results in a variant form of the human disease involving pituitary hormone insufficiencies but not the deafness and neck stiffness that are correlated with LHX3 nervous system functions." (PMID 23861948, 2013).
craniopharyngioma (2 papers, 2021). A benign, partly cystic, epithelial tumor of the sellar region, presumably derived from Rathke pouch epithelium. "The study included eight patients with parasellar tumors (five craniopharyngiomas, three hypothalamic astrocytomas) and five patients with congenital midline malformations (four septo- optic dysplasia, one LHX3 mutation)." (PMID 34206290, 2021). "In turn, mutations of other transcription factors (e.g., PIT-1/POU1F1, PROP-1, LHX3, SOX2, SOX3, OTX2 and HESX1) lead to congenital MPHD, while hypothalamic-pituitary tumours (e.g., craniopharyngiomas), their treatment regimens or traumatic brain injuries result in acquired MPHD." (PMID 34445772, 2021).
dwarfism (1 paper, 2011). "The detection of two mutations in LHX3 supports our conclusion that this gene is involved in the dwarfism phenotype in GSD, since the odds that we would have detected two mutations in a strong positional candidate gene by chance are negligible." (PMID 22132174, 2011).
embryonic carcinoma (1 paper, 2017). "To test whether the Isl1-Lhx3 complex directly activates transcription via Lhx3-Peak-A, even without initiating MN fate specification, we performed luciferase reporter assays in cultured mouse embryonic carcinoma P19 cells." (PMID 28451636, 2017).
hypogonadotropic hypogonadism (1 paper, 2025). Abnormal ovarian or testicular function due to insufficient hormonal stimulation from the hypothalamic-pituitary axis. "In mice, LHX3 mutations lead to significant decreases in LH and FSH expression, resulting in hypogonadotropic hypogonadism." (PMID 41200545, 2025).
Merkel cell carcinoma (1 paper, 2025). "Here, we show that MCPyV+ Merkel cell carcinoma is defined by neuroendocrine-lineage core regulatory (CR) transcription factors (TFs) (ATOH1, INSM1, ISL1, LHX3, POU4F3, and SOX2) that were essential for tumor survival and that co-bound chromatin with the viral small T antigen at super enhancers." (PMID 41392987, 2025).
pituitary dwarfism (1 paper, 2011). Proportionately decreased bodily growth due to failure of the pituitary gland to produce an adequate supply of growth hormone. "We found that pituitary dwarfism in GSD is associated with a deletion of a 7 bp repeat in intron 5 of LHX3, a gene encoding another important transcription factor involved in pituitary development." (PMID 22132174, 2011). "In conclusion, a contraction of a DNA repeat in intron 5 of canine LHX3 leads to deficient splicing and is associated with pituitary dwarfism." (PMID 22132174, 2011). "Our results show that mutations in the LHX3 gene are associated with pituitary dwarfism of GSD." (PMID 22132174, 2011). "Because the endocrinological phenotype of humans with LHX3 mutations and LHX3-knockout mice is consistent with the phenotype of the GSD dwarfs, we considered LHX3 an excellent candidate gene for involvement in pituitary dwarfism in this breed." (PMID 22132174, 2011).
spinocerebellar ataxia (1 paper, 2025). "In the KO network, LHX3 was in the same subnetwork as CWF19L1, which is a gene commonly associated with spinocerebellar ataxia." (PMID 40258535, 2025).
tumor (4 papers, 2009 to 2025). "Lhx3 and Lhx4 regulate proliferation and differentiation of pituitary-specific cell lineages and are expressed in subsets of lymphocytes and thymocyte tumor cell lines." (PMID 19997623, 2009).
LHX3 also shares sentences with these, for which no sentence is quoted: breast carcinoma (2 papers); endocrine diseases (2); Gonadotropin deficiency (2); Septo-optic dysplasia (2); acute lymphoblastic leukemia (1); adenosquamous carcinoma (1); adolescent idiopathic scoliosis (1); astrocytoma (1); brain injuries (1); cancer (1); cerebral malformation (1); cerebral tumor (1); cervical cancer (1); chronic myeloid leukemia (1); clear cell renal cell carcinoma (1); colorectal cancer (1); congenital hypogonadotropic hypogonadism (1); congenital hypopituitarism (1); follicular lymphoma (1); head and neck squamous cell carcinoma (1); hearing loss (1); holoprosencephaly (1); hypothyroidism (1); infection (1); motor neuron diseases (1); Nephroblastoma (1); ovarian carcinoma (1); pulmonary diseases (1); Sepsis (1); thyroid cancer (1).
A further 1 disease shares a sentence with LHX3 in 1 paper.